TPM4 (tropomyosin 4)
Diseases named in the same sentence as TPM4 in open-access papers (continued):
Sharing a sentence is not in itself a finding about the gene and the disease.
COVID-19 (1 paper, 2021). A disease caused by infection with severe acute respiratory syndrome coronavirus 2. "Our studies have demonstrated that a crucial factor in platelet biogenesis TPM4 is inhibited (FC-1.94, p < 0.001) in severe cases, thereby providing novel biological insight into COVID-19 severity." (PMID 33995121, 2021).
diabetes (1 paper, 2016). "The high variance impairs statistical confidence that the lower expression of HMW isoforms from TPM1 and TPM4 is associated with diabetes." (PMID 27649540, 2016). "In diabetes, expression of HMW isoforms from TPM1 were markedly decreased (0.55 v 1.00; p = 0.019) but HMW isoforms from TPM4 were not significantly different (0.76 v 1.00; p = 0.205)." (PMID 27649540, 2016). "Expression of LMW isoforms from these genes was not different in diabetes (TPM1: 1.00 v 0.94, p = 0.66; TPM4: 1.00 v 0.81, p = 0.14)." (PMID 27649540, 2016).
ductal breast carcinoma in situ (1 paper, 2017). A carcinoma entirely confined to the mammary ducts. "In addition, patients with invasive ductal breast carcinoma show decreased TPM4 expression compared with patients with ductal breast carcinoma in situ, and low TPM4 expression is associated with poor prognosis." (PMID 28431393, 2017). "In addition, TPM4 expression is decreased in invasive ductal breast carcinoma compared with ductal breast carcinoma in situ and the low level of expression is associated with a poor prognosis." (PMID 28431393, 2017). "Patients with invasive ductal breast carcinoma showed decreased TPM4 expression compared with patients with ductal breast carcinoma in situ." (PMID 28431393, 2017).
glioblastoma (1 paper, 2023). The most malignant astrocytic tumor (WHO grade IV). "Moreover, we also observed that the level of TPM4 was higher in glioblastoma than in other histological types." (PMID 36639743, 2023).
Hypertension (1 paper, 2024). The presence of chronic increased pressure in the systemic arterial system. "However, the specific relationship between TPM4 and hypertension has not yet been established." (PMID 38732116, 2024).
lentivirus infection (1 paper, 2023). Virus diseases caused by the Lentivirus genus. "In our previous study, after shRNA lentivirus infection, the knockdown efficiency of shTPM4 was 71.1%, and the knockdown of TPM4 inhibited GC cell proliferation." (PMID 36993958, 2023).
liver fibrosis (1 paper, 2025). "Hepatic TPM4 expression was higher in a mouse model of CCl4-induced liver fibrosis than in control mice." (PMID 40689527, 2025). "TPM4 is also involved in regulating epithelial–mesenchymal transition, a key mechanism behind liver fibrosis development." (PMID 40689527, 2025).
lymph node metastasis (1 paper, 2025). "Subsequent validation across multiple GEO datasets revealed that only TPM4 showed consistently elevated expression in the lymph node metastasis group with statistical significance." (PMID 40740237, 2025).
osteoporosis (1 paper, 2017). A condition of reduced bone mass, with decreased cortical thickness and a decrease in the number and size of the trabeculae of cancellous bone (but normal chemical composition), resulting in increased fracture incidence. "Previous studies from our group have supported the contribution of GPD2, TPM4 and GSN to osteoporosis risk." (PMID 27878450, 2017).
pancreatic cancer (1 paper, 2022). "In pancreatic cancer, TPM4 is thought to serve as a prognostic biomarker for pancreatic cancer." (PMID 35892971, 2022).
papillary thyroid cancer (1 paper, 2025). "Our study elucidates a novel mechanism whereby the hypoxic microenvironment in papillary thyroid cancer drives TPM4 upregulation, subsequently inducing epithelial-mesenchymal transition in tumor cells and promoting lymph node metastasis." (PMID 40740237, 2025).
prostate carcinoma (1 paper, 2021). A carcinoma that arises from epithelial cells of the prostate gland. "In this context, differences in protein expression (SATB1, SPIN1, TBB5, VIME, TPM4) between benign prostate tissue and prostate cancer with respect to clinicopathological risk factors, tumor heterogeneity and genomic instability were assessed." (PMID 34961766, 2021). "Despite their tumor biology functions, neither SATB1, SPIN1, VIME, TBB5 nor TPM4 are yet being used in routine risk assessment for prostate cancer." (PMID 34961766, 2021).
psoriasis (1 paper, 2024). An autoimmune condition characterized by red, well-delineated plaques with silvery scales that are usually on the extensor surfaces and scalp. "The list of differentially expressed proteins also includes immune-related molecules, such as in TPM4 [FC = 2.2; p = 0.009], Serglycin (SRGN) [FC = 0.08; p = 0.03] or antioxidant proteins, such as GSTP1 [FC = 5.3; p = 0.03] in psoriasis." (PMID 39062477, 2024).
sarcoma (1 paper, 2014). A usually aggressive malignant neoplasm of the soft tissue or bone. "The identification of fusion genes such as SYT-SSX1/SSX2, PAX3-FOXO1, TPM3/TPM4-ALK, BCOR-CCNB3 and EWS-FLI1 in human sarcomas has provided important insight into the diagnosis and targeted therapy of sarcomas." (PMID 25300797, 2014). "The identification of fusion genes such as SYT-SSX1/SSX2, PAX3-FOXO1, TPM3/TPM4-ALK and EWS-FLI1 in human sarcomas has provided important insight into the diagnosis and targeted therapy of sarcomas." (PMID 25300797, 2014).
thrombosis (1 paper, 2020). "These genes included STIM1 and C4BPA, which impact platelet reactivity and/or thrombosis risk, as well as MASTL and TPM4, which influence megakaryo-thrombopoiesis." (PMID 32600345, 2020).
thyroid cancer (1 paper, 2025). "The results of wound healing and transwell assays demonstrated that TPM4 knockdown effectively inhibited migration and invasion of thyroid cancer cells." (PMID 40740237, 2025). "Correlation analysis revealed a strong positive association between HIF1A expression and TPM4 levels in PTC cells, further supporting the interconnected nature of hypoxia response and TPM4-mediated EMT processe in thyroid cancer progression." (PMID 40740237, 2025). "To investigate the role of TPM4 in PTC with LNM, we performed RT-qPCR and Western blot analyses to examine TPM4 mRNA and protein levels in clinical samples and thyroid cancer cell lines." (PMID 40740237, 2025). "Given the absence of prior studies examining TPM4 expression and function in thyroid cancer, we undertook this investigation." (PMID 40740237, 2025).
tongue tumor (1 paper, 2018). "The present study identified cofilins (CFL1 and CFL2) and tropomyosin family proteins (TPM3 and TPM4) are significantly upregulated, in contrast, myosin family proteins (MYL2, MYL4 and MYLPF) were downregulated in tongue tumor samples as compared to normal samples." (PMID 29371635, 2018).
triple-negative breast carcinoma (1 paper, 2013). An invasive breast carcinoma which is negative for expression of estrogen receptor (ER), progesterone receptor (PR), and human epidermal growth factor receptor 2 (HER2). "The opposing expression patterns of the TPM4 isoforms were confirmed in the estrogen receptor-positive and triple-negative breast cancer sample." (PMID 23594586, 2013).
Type 2 diabetic (1 paper, 2016). "The results of this study strongly indicate that there are decreased levels of expression of HMW isoforms from TPM1 and TPM4 in leukocytes from Type 2 diabetic patients and that these are due to elevated levels of inflammatory cytokines in those patients." (PMID 27649540, 2016). "The aim was to determine changes in expression of isoforms from TPM1 and TPM4 genes in leukocytes from Type 2 diabetic patients and to use the leukocyte cell line THP1 to identify possible mediators of changes in the patients." (PMID 27649540, 2016). "We have investigated the expression of tropomyosin isoforms from TPM1 and TPM4 in patients with Type 2 diabetes." (PMID 27649540, 2016). "Expression of TPM4 HMW isoforms were not significantly different (0.76 v 1.00, p = 0.21) in leukocytes from Type 2 diabetic patients compared to normal controls." (PMID 27649540, 2016).
vitamin D deficiency (1 paper, 2023). A nutritional condition produced by a deficiency of VITAMIN D in the diet, insufficient production of vitamin D in the skin, inadequate absorption of vitamin D from the diet, or abnormal conversion of vitamin D to its bioactive metabolites. "The results showed that vitamin D deficiency led to the abnormal expression of CFB, TPM4, C9, ICOSL, and PI16." (PMID 36178657, 2023).
tumor (32 papers, 2006 to 2025). "We investigated the association between TPM4 expression and immune cell infiltration within the tumor microenvironment (TME)." (PMID 36993958, 2023). "ScRNA-seq analysis suggested that higher TPM4 was mainly attributed to tumor cells and macrophages and associated with tumor cell progression and macrophage polarization." (PMID 36138856, 2022). "The downregulation of the miR leads to TPM4 overexpression, this modifies the architecture of the cell cytoskeleton contributing to increase the invasiveness of the tumour and associating with a poor prognosis." (PMID 34575979, 2021). "Furthermore, according to the analysis of immune cell infiltration, TPM4 was associated with tumor infiltration of a variety of immune cells." (PMID 36639743, 2023). "Finally, the mechanism proposed is that the downregulation of miR-133a in CRC leads to TPM4 overexpression, modifying the cell cytoskeleton, increasing the invasiveness of the tumour and associating with a poor prognosis." (PMID 34575979, 2021). "TPM1 and TPM4 genes encode proteins associated with cardiovascular and neoplastic disease." (PMID 27649540, 2016). "Our study made several novel contributions: we first demonstrated that hypoxia-induced TPM4 upregulation in PTC influences tumor cell invasion and migration, facilitating lymph node metastasis." (PMID 40740237, 2025). "First, deeper mechanistic investigation of the hypoxia-TPM4 axis in tumor cell metastasis is needed." (PMID 40740237, 2025). "Our findings illuminate a novel mechanism whereby the hypoxic tumor microenvironment promotes lymph node metastasis in PTC through TPM4-mediated activation of EMT signaling, providing new insights into LNM of PTC." (PMID 40740237, 2025). "Our results demonstrated that as tumor cells progress through differentiation, hypoxia pathway enrichment coincides with TPM4 upregulation and EMT pathway activation." (PMID 40740237, 2025). "Our analysis revealed that TPM4 and LOXL1 exhibited strong associations with lymph node metastasis and tumor size in PTC." (PMID 40740237, 2025). "Chi-square analysis comparing patients with high and low TPM4 expression in tumor samples demonstrated significant differences in lymph node metastasis status (N stage) between the two groups." (PMID 40740237, 2025). "As an actin-binding protein, TPM4 belongs to the protomyosin family, which can enhance the migration of tumour cells by changing the actin cytoskeleton." (PMID 37328795, 2023). "First, we used the TCGA and GTEx databases to determine the expression of TPM4 in various tumor and normal tissue types." (PMID 36639743, 2023). "The outcomes of these experiments showed that TPM4 is a key oncogene that promotes tumor invasion and cell migration in GC." (PMID 36993958, 2023). "And there were also significantly more Ki67+ tumor cells in Tpm4 overexpression ESCC than control tumors." (PMID 35418165, 2022). "Fluorescence living imaging showed the Tpm4 overexpressed tumors had a dramatically more vigorous fluorescence intensity than the control tumor." (PMID 35418165, 2022). "Our results demonstrated that the expression of TPM2 and TPM4 were negatively correlated with tumor purity (p < 0.05) indicating highly expression in HCC microenvironment." (PMID 34850589, 2022). "Our findings demonstrate that SFTA1P can promote tumor progression by mediating the degradation of TPM4 mRNA through its interaction with PTBP1 protein." (PMID 36344495, 2022). "It turned out that TPM4 was mainly expressed and activated in developmental or established tumor cells, especially in state 5 of tumor cells." (PMID 36138856, 2022). "It was revealed that NORAD functioned as a tumor promoter to sponge miR-577 thus elevating TPM4 in OSCC, which indicated that NORAD was worthy to be studied as a target for the treatment of OSCC." (PMID 34991683, 2022).
tumor (continued). "Since the modification of cell cytoskeleton is a fundamental step for tumour invasiveness, it would be interesting to dissect the role of TPM4 also in CRC physiology." (PMID 34575979, 2021). "In these sections TPM4 organised fibres staining is only detectable in the vascular tissue, since TPM4 is present also in the smooth muscle of arterioles of the neo vascularised tumour region." (PMID 34575979, 2021). "Briefly, we have identified TPM4 as upregulated salivary protein in patients with OSCC, which plays a central role in stabilizing cytoskeleton actin filaments, probably linked with tumor tissue remodeling." (PMID 31804537, 2019). "Both decreased and increased TPM4 expression has been observed in human cancers, depending on the tumor type." (PMID 31278140, 2019). "Furthermore, we identified TPM4 as significantly upregulated in the LNM tumor group (adjusted p-value = 3.54e-34, |log2FC| = 0.64)." (PMID 40740237, 2025). "Besides, TPM4 expression was found to correlate with immune cell infiltration, immune checkpoint (ICP) gene expression, the tumor mutational burden (TMB), and microsatellite instability (MSI)." (PMID 36993958, 2023). "The tumor-suppressive effect of miR-133a may be related to the Mir-133a-dependent regulation of TPM4 expression." (PMID 37686101, 2023). "The expression of TPM4 was also confirmed to be significantly correlated with the mutation levels of five MMR genes in pancreatic cancer and the level of immune infiltration in the tumor microenvironment." (PMID 37686101, 2023). "TPM4 could be expressed by tumor cells, macrophages, oligodendrocytes, and T cells in the tumor microenvironment (TME)." (PMID 36138856, 2022). "Also, the expression of TPM4 in tumor and normal adjacent tissues was detected by RT-qPCR assay and searched online." (PMID 34991683, 2022). "Emerging evidence indicates that TPM4 is a crucial modulator during tumor development." (PMID 36138856, 2022). "In all tumour cell lines, only a small amount of TAp63 is detectable in steady-state level, in accordance with its tumour suppressor role, even if the TAp63 ectopic expression retains the possibility to drive the TPM4 expression." (PMID 34575979, 2021). "We propose here that miR-133a tumour suppressor role could be related also to the miR-133a-dependent regulation of TPM4 expression." (PMID 34575979, 2021). "Indeed, actin-TPM4 microfilaments are involved in contraction, cell morphology, cell motility and intracellular vesicle transport, recent evidence also suggested its crucial role in tumour development." (PMID 34575979, 2021). "CircASH2 drives phase separation of YBX1 to increase TPM4 transcripts degradation and suppresses HCC metastasis by altering the tumor cytoskeleton structure." (PMID 38969650, 2024). "It is worth noting that TPM4 expression exhibited an upregulating trend in tumor cells and macrophages as the WHO grade increased, in contrast to the uniform distribution of TPM4 expression among oligodendrocytes and T cells across different WHO grades." (PMID 36138856, 2022). "While AASEs of tumor-related genes, such as ARMC3, TPM4, and TNFRSF12A had higher inclusion levels in G3." (PMID 35989380, 2022). "In agreement with its function in the self-renewal and migration of esophageal epithelial cells, the TPM4 expression was positively correlated with multiple related pathways, including EMT, stem cell maintenance, tumor invasiveness." (PMID 35418165, 2022). "In conclusion, the data from our studies revealed that NORAD was a tumor promoter and it accelerated the progression of OSCC by targeting miR-577/TPM4 axis." (PMID 34991683, 2022).
tumor (continued). "This up-regulation expands to other potential tumor markers including A1AT1, tropomyosin-4, TUBB3, ACTN4, DDX3X, LMNB1, PARP and vimentin." (PMID 29109428, 2017). "High (HMW) and low (LMW) molecular weight isoforms from TPM1 and TPM4 are altered in several cancer cells and the 3'UTR of TPM1 mRNA is tumour suppressive." (PMID 27649540, 2016). "However, comprehensive studies on the relevance of TPM4 expression in tumor immune cell infiltration, ICP gene expression, TMB, MSI, NEO, ceRNA, drug sensitivity, and the pan-cancer mechanism of action of TPM4, especially in GC, have seldom been conducted." (PMID 36993958, 2023). "Additionally, the levels of tumor-promoting genes (Lrp5, MMP9, Runx2, and Snail) were increased by TGFβ and CXCL5, while they were reduced by TPM4, ANXA6, and Trail." (PMID 34230453, 2021). "This miRNA is less expressed in DLD-1, HCT-116 rather than CaCo-2 tumour cell lines, and accordingly higher TPM4 mRNA levels were found in DLD-1 rather than in CaCo-2." (PMID 34575979, 2021). "Moreover, we found TPM4 and CCDC80, which were reported to exert a tumor repression activity, to be upregulated due to SUV39H2 knockdown." (PMID 30348215, 2018). "Furthermore, six tumor progression genes (GNAI2, ODC1, APP, TNFRSF12A, BASP1, and LARP6) and nine migration and metastasis‐related genes (MSN, FLOT1, LAMB3, MYL9, ITGB1, FTH1, TPM4, and PMEPA1), which could explain the invasive characteristics of SCC, were identified." (PMID 40776410, 2025).